YWHAZP6 (tyrosine 3-monooxygenase/tryptophan 5-monooxygenase activation protein zeta pseudogene 6)
Gene: Processed pseudogene on chromosome 9 (34,922,184 to 34,922,921, reverse strand). Ensembl gene ENSG00000215199.
Diseases named in the same sentence as YWHAZP6 in open-access papers:
YWHAZP6 is named in the same sentence as 1 disease in open-access papers, as found by Europe PMC text mining. Sharing a sentence is not in itself a finding about the gene and the disease. The quoted sentences say what the papers report.
psoriatic arthritis (1 paper, 2024). Joint inflammation associated with psoriasis. "A study of T cells from the blood and synovial fluid of psoriatic arthritis patients revealed the expression of YWHAZP3 and YWHAZP10 in both leukocytes and T cells; the expression of YWHAZP1, YWHAZP5, and YWHAZP6 in leukocytes only; the expression of YWHAZP2 in T Cells only." (PMID 38674334, 2024).